RUFY1 (RUN and FYVE domain containing 1)
Description:
Activating adapter involved in cargo sorting from early/recycling endosomes. Regulates retrieval of proteins from endosomes to the trans-Golgi network through interaction with the dynein-dynactin complex. Dual effector of RAB4B and RAB14, mediates a cooperative interaction allowing endosomal tethering and fusion. Binds phospholipid vesicles containing phosphatidylinositol 3-phosphate and participates in early endosomal trafficking. In oocytes, self-assembles to form a protein matrix which hold together endolysosomes, autophagosomes and proteasomes and generate non-membrane-bound compartments called endo-lysosomal vesicular assemblies (ELVAs). In immature oocytes, ELVAs sequester ubiquitinated protein aggregates and degrade them upon oocyte maturation (By similarity).
Synonyms: RABIP4; ZFYVE12; FLJ22251
Tractability: Antibody: UniProt places it where antibodies can reach, with high confidence. PROTAC: ubiquitination databases record sites on it; its protein half-life has been measured.
Gene: Protein-coding gene on chromosome 5 (179,550,542 to 179,610,012, forward strand). Ensembl gene ENSG00000176783.
Subcellular location: Early endosome membrane
Subcellular location (Human Protein Atlas): Cytosol; Vesicles; Nuclear speckles
Pathways (Reactome):
Metabolism: Synthesis of PIPs at the plasma membrane
Gene Ontology:
Molecular function: protein binding; protein-macromolecule adaptor activity; SH2 domain binding; SH3 domain binding; metal ion binding
Biological process: early endosome to Golgi transport; endosomal vesicle fusion; regulation of endocytosis; phosphatidylinositol biosynthetic process; protein transport
Cellular component: cytosol; early endosome membrane; endosome; cytoplasm
Genetic constraint (gnomAD): Loss-of-function variants: 38 observed, 61.23 expected, observed/expected ratio (o/e) 0.62, 90% interval 0.48 to 0.81. The synonymous counts are far from expectation, so gnomAD's model fits this gene poorly and the ratio says little. Missense variants: 690 observed, 616.57 expected, observed/expected ratio (o/e) 1.12, 90% interval 1.05 to 1.19. Synonymous variants: 315 observed, 253.56 expected, observed/expected ratio (o/e) 1.24, 90% interval 1.13 to 1.36.
Homologues: Orthologues: chimpanzee RUFY1 (99% identical), pig RUFY1 (92% identical), rat Rufy1 (92% identical), rabbit RUFY1 (92% identical), mouse Rufy1 (91% identical), guinea pig RUFY1 (90% identical), dog RUFY1 (87% identical), macaque RUFY1 (84% identical), zebrafish rufy1 (61% identical), tropical clawed frog rufy1 (60% identical), Drosophila melanogaster CG31064 (37% identical), Drosophila melanogaster CG6051 (12% identical), and 1 more. Paralogues in human: RUFY2 (53% identical), RUFY3 (43% identical), ZFYVE26 (18% identical), PLEKHM2 (17% identical), SNX29 (16% identical), RUNDC3B (16% identical), ZFYVE28 (16% identical), RUNDC3A (15% identical), ZFYVE1 (13% identical), ZFYVE19 (10% identical), ZFYVE16 (10% identical), PLEKHF1 (7% identical), and 1 more.
Diseases named in the same sentence as RUFY1 in open-access papers:
RUFY1 is named in the same sentence as 11 diseases in open-access papers, as found by Europe PMC text mining. Sharing a sentence is not in itself a finding about the gene and the disease. The quoted sentences say what the papers report.
gastric cancer (6 papers, 2019 to 2024). A primary or metastatic malignant neoplasm involving the stomach. "Gene silencing of RUFY1 expression in gastric cancer cells was associated with its progression." (PMID 39057100, 2024). "RUFY1 has been reported to promote disease progression in gastric cancer and HECTD4 was a favorable prognostic marker in head and neck cancer according to the Human Protein Atlas database." (PMID 35625741, 2022). "Evidence shows that RUFY1, as a tumor promoter gene, plays an important role in the development of gastric cancer." (PMID 33042807, 2020). "A recent study has reported the silencing of RUFY1 expression in gastric cancer cells." (PMID 32905102, 2020). "Gastric cancer progression is significantly increased upon PODXL expression, a phenotype reduced by concomitant RUFY1 silencing." (PMID 32850870, 2020). "Targeting PODXL/RUFY1 complex may improve the prognosis of gastric cancer (GC) and provide new treatment opportunities for GC patients." (PMID 33042807, 2020).
breast carcinoma (2 papers, 2021 to 2024). "Hypermethylation of sites close to the RUFY1 gene is associated with mammographic density and may be an important epigenetic signature related to breast cancer risk." (PMID 39057100, 2024). "The RUFY1 protein is suggested as a biomarker of epithelial-mesenchymal transition and has relevance to the immune system in the metastasis of breast cancer in humans." (PMID 39057100, 2024).
type 2 diabetes mellitus (2 papers, 2017 to 2020). A type of diabetes mellitus that is characterized by insulin resistance or desensitization and increased blood glucose levels. "Five polymorphisms—rs139421991 of CAT, rs189305583 of PDCL2, rs138313632 of RUFY1, rs139012426 of LOC100505549, and rs76974938 of C21orf59—may be novel determinants of type 2 diabetes mellitus." (PMID 29113320, 2017).
food allergy (1 paper, 2022). Gastrointestinal disturbances, skin eruptions, or shock due to allergic reactions to allergens in food. "RUFY1, in context of aero‐allergens, presented in a different methylation direction between the studies, while SCART1, in context of food allergy, did not." (PMID 36225266, 2022).
lung carcinoma (1 paper, 2020). "In addition, RUFY1, DEPDC7, and IRF4 were reported to be involved in lung cancer." (PMID 33051402, 2020).
cancer (3 papers, 2020 to 2024). A tumor composed of atypical neoplastic, often pleomorphic cells that invade other tissues. "The decrease in RUFY1 in this context may indicate a greater risk of cancer aggressiveness and metastasis, affecting disease progression." (PMID 39057100, 2024). "PHF1, RUFY1, and CDR2 are highly expressed in some cancers, positively correlated with tumor progression." (PMID 34571936, 2021). "Depletion of RUFY1 inactivates the PI3K/AKT, NF-κB and MAPK/ERK signaling pathways and reduces drastically migration and invasion of cancer cells in vitro." (PMID 32850870, 2020). "Like RUFY1, a role for RUFY2 in various cancer has been reported." (PMID 32850870, 2020).
tumor (3 papers, 2019 to 2021). "Accordingly, RUFY1 can regulate the transport of integrin in the process of cell migration and tumor invasion." (PMID 31772661, 2019).
RUFY1 also shares sentences with these, for which no sentence is quoted: Alzheimer disease (1 paper); head and neck cancer (1); non-small cell lung carcinoma (1); schizophrenia (1).